LEP (leptin)
Diseases named in the same sentence as LEP in open-access papers (continued):
Sharing a sentence is not in itself a finding about the gene and the disease.
tumor (777 papers, 2006 to 2026). "High leptin expression has also been associated with poor prognosis and invasion of tumor cells by matrix metalloproteinases (MMPs) overexpression that induces the degradation of the extracellular matrix components." (PMID 40227577, 2025). "Hormonal dysregulation is another contributing factor, as obesity is associated with increased leptin, a pro‐tumorigenic hormone, and decreased adiponectin, an anti‐tumorigenic hormone, which alters immune responses and tumor growth dynamics." (PMID 40387523, 2025). "Obese individuals often exhibit high leptin levels, leading to leptin resistance, which has been implicated in tumor development." (PMID 40387523, 2025). "Whilst the underlying mechanisms are unclear, adipokines, including leptin, oxidative phosphorylation, a hypoxic tumour microenvironment, and the gastrointestinal microbiome have all been postulated to play a role." (PMID 40227712, 2025). "Preoperative serum leptin and overexpression of the leptin receptor (leptin-R) were linked to tumor invasiveness and progression of RCC." (PMID 41010935, 2025). "Positive correlations were observed between the HOMA-IR and ITLN1 and CD295 SNPs, as well as a positive correlation between LEP and tumor grade, establishing connections between genetic variants and metabolic phenotypes." (PMID 41221514, 2025). "Leptin also promotes M2 macrophage differentiation in the tumor microenvironment, a process associated with tumor progression and lymph node metastasis." (PMID 40227577, 2025). "Leptin is a satiety hormone associated with pro-inflammatory, anti-apoptotic, and pro-angiogenic actions, thus exerting a relevant role in the promotion of tumor growth 87; indeed, its serum concentrations were higher in mice fed with a high-fat diet." (PMID 38164270, 2024). "In general, we suggest that leptin-induced metabolic changes are required to sustain features of increased tumor aggressiveness associated with metastasis." (PMID 38228661, 2024). "To offer further insights into lipid accumulation leading to tumorigenesis, we used a leptin-deficient (obese) mouse model and found that loss of Sirt6 accelerates tumor formation in the liver, accompanlied by reduced CD4+ and CD8+ T cells in the liver." (PMID 38332150, 2024). "NGF blockade can decrease nociception, restrict tumor proliferation, and reduce weight loss by leptin and pro-inflammatory cytokines production." (PMID 39099944, 2024). "Leptin derived from adipocytes regulates the expression of genes associated with tumor progression, such as those involved in adhesion, invasion, angiogenesis, and apoptosis." (PMID 39199587, 2024). "Leptin-deficient mouse models have demonstrated reduced tumor growth rates and decrease in tumor size." (PMID 39525621, 2024). "The binding of leptin to its receptor can activate several signaling pathways associated with tumor progression, including TGF-β, JAK/STAT, PI3K, HIF, and MAPK pathways." (PMID 38571500, 2024). "Leptin, through Heat Shock Protein 90, is able to modulate the expression, at the post-transcriptional level, of the tumor susceptibility gene 101, known to be a key component of the endosomal sorting complex required for transport I." (PMID 37509120, 2023). "Changes in leptin and the leptin–adiponectin ratio suggested an association with the aggressiveness of the tumor histology." (PMID 37444627, 2023). "Recent studies show that elevated leptin levels are associated with the degree of myometrial infiltration, the occurrence of secondary tumor foci in lymph nodes also associated with lymphatic vessel involvement, and a low survival rate." (PMID 37190027, 2023). "Revealing the mechanisms of leptin causing tumor formation and suppression of these mechanisms can be considered as a treatment strategy." (PMID 37155466, 2023).
tumor (continued). "Leptin, associated with tumour growth, angiogenesis, and inflammation, modulates the adipokine profile of tumour adipocytes, influencing their paracrine signalling to nearby cancer and stromal cells." (PMID 38136392, 2023). "On the other hand, in decreased leptin concentration conditions (leptin-deficient tumors), a decrease in tumor cell proliferation and tumor growth was observed." (PMID 37048534, 2023). "TB AAV-VHL effectively restored VHL and decreased leptin expression in adipocytes of tumour-bearing mice, and reversed tumour-associated adipose tissue lipolysis and browning." (PMID 37620316, 2023). "Leptin normally circulates through the bloodstream, which we corroborated by enzyme-linked immunosorbent assays (ELISAs) of blood plasma from non-tumour bearing control mice." (PMID 36450983, 2022). "Leptin is associated with tumor growth and promotion for its mitogenic, antiapoptotic, pro-angiogenic, and pro-inflammatory effects, while also promoting invasion and migration." (PMID 35164764, 2022). "Forced expression of miR-506 or miR-150 significantly increased the susceptibility of Leptin+ cells to palbociclib treatment by inhibiting colony and tumor spheroid formation, and CD44 expression in Panc-1 and MiaPaCa-2 cells." (PMID 37529006, 2022). "In contrast, tumor growth was positively associated with serum leptin levels, and negatively with serum ghrelin levels." (PMID 35361802, 2022). "Together, these results suggest that loss of GLS in tumor endothelium affects leptin levels in tumors." (PMID 36381236, 2022). "Another possible explanation for higher risk of relapse with low serum Leptin levels is tumour dormancy induced by energy deficiency." (PMID 35216457, 2022). "We demonstrated that GLS loss in tumor endothelium leads to decreased leptin but increased leptin receptor levels in E0771 tumors." (PMID 36381236, 2022). "Mechanistically, loss of GLS in tumor endothelium resulted in decreased leptin levels, and exogenous recombinant leptin rescued tumor growth defects in GLSECKO mice." (PMID 36381236, 2022). "Leptin signalling has been implicated as a driver of angiogenesis in colorectal cancer and glioblastoma, resulting in metastasis and tumour growth." (PMID 34572888, 2021). "Several studies also reported that the expression of leptin and its receptor are associated with greater tumor size in Chinese PTC patients albeit with some differences in the results." (PMID 33587254, 2021). "Both in vitro and in vivo studies have shown that leptin stimulates tumor growth and cell migration, thereby increasing the risk of distant metastasis." (PMID 33864589, 2021). "In BC patients, high circulating leptin levels increase the risk of tumor progression, since its possible involvement in the autocrine loop that sustains the expression of an inflammatory phenotype." (PMID 33670492, 2021). "Our results showed a significant association of LEP protein overexpression with several clinicopathological variables, mainly tumor subtype, LVI, age of menarche, tumor size and stage (p < 0.04)." (PMID 34884678, 2021). "Estradiol was significantly correlated with tumor T stage (P = 0.002) and leptin was significantly associated with perineural invasion (P = 0.014)." (PMID 34970222, 2021). "The expression of leptin is increased in human colorectal tumors and is associated with tumor progression and clinic pathological parameters." (PMID 32486076, 2020). "Leptin is an important regulator of adipose tissue mass and has been associated with tumor cell growth." (PMID 33299884, 2020). "The tumor suppressor activities of leptin on HCC have been associated with leptin interference with the immune system." (PMID 33316927, 2020). "Leptin is known to influence tumour-associated macrophages (TAMs), a critical component in the tumour microenvironment and a major source of inflammatory cytokines." (PMID 32033341, 2020).
tumor (continued). "The overexpression of leptin and down-regulation of adiponectin are most commonly associated with progressing or poor prognosis tumours." (PMID 32512860, 2020). "It has been reported that higher leptin expression is associated with increased tumor metastasis and poorer prognosis." (PMID 32836215, 2020). "sOB-R level is regulated by plasma leptin concentration, lipotoxicity, and endoplasmic reticulum stress; a disturbance in its level causes several metabolic conditions and neoplasms." (PMID 32316577, 2020). "In azoxymethane (AOM) induced murine colon cancer model, Leptin-deficient (ob/ob) and leptin receptor-deficient (db/db) mice showed inhibited tumor growth through Wnt signaling pathway." (PMID 32486076, 2020). "The elevated levels of serum leptin are associated with tumor progression, while the adiponectin diminishes the proliferation of tumor cells." (PMID 33046976, 2020). "Our data strongly suggest that leptin is associated with the establishment of a more aggressive phenotype of the tumor cells promoting local invasion and eventually metastasis of tumor cells." (PMID 31671408, 2019). "The possible cause is the high concentration of leptin, insulin, insulin-like growth factor-I and low of adiponectin, which together, are likely to promote tumor growth and progression." (PMID 31185699, 2019). "Similar to leptin, the association of leptin receptor expression across the grades of the tumor was statistically significant with p value being 0.018, as assessed via Fisher’s exact test." (PMID 30803210, 2019). "In tumor-associated macrophages, leptin induced the expression of IL-18 via NF-kB, possible contributing to tumor progression." (PMID 29910742, 2018). "Leptin acts as a growth factor for different kinds of tumor cells, causes rapid nuclear translocation of β-catenin, and activates other components of the Wnt/β-catenin pathway." (PMID 28533765, 2017). "It is generally indicated that TNF-α promotes progression of RCC by enhancing tumor invasion and epithelial-mesenchymal transition and that lower serum adiponectin levels and higher serum leptin levels are associated with higher aggressiveness of RCC20–23." (PMID 28986556, 2017). "Tumor recurrence was significantly associated with cases of low leptin immunostaining scores (P = 0.0023)." (PMID 29121911, 2017). "Next, we compared the proliferative activity of leptin in 1321N1 cells with known mitogens implicated in tumor pathogenesis such as EGF or sPLA2-IIA." (PMID 28249041, 2017). "The anti-tumor action of the FXR ligand was associated with the inhibition of several leptin-induced pathways, such as JAK2/STAT3, AKT and MAPK." (PMID 26899873, 2016). "The tumor burden was associated with circulating cholesterol, triglyceride, glucose, insulin, leptin and adiponectin concentrations." (PMID 26959117, 2016). "Plasma leptin concentrations significantly increased with adiposity, were reduced to control levels with weight loss, and negatively correlated with tumor latency." (PMID 27042159, 2016). "Elevated expression of leptin and ObRb is associated with faster tumor recurrence and mortality in human grade-III invasive breast tumors." (PMID 26839577, 2016). "These pleiotropic effects of leptin on macrophages exist despite the fact that leptin induces downregulation of its own receptor in these cells, as we showed for both peripheral and tumor-associated macrophages." (PMID 25599228, 2015). "Extending these findings to tumour angiogenesis, recent studies have implicated intratumoral leptin to exert proangiogenic effects stimulating tube formation and proliferation of endothelial cells." (PMID 25650072, 2015).
tumor (continued). "Our results revealed that only in overweight and obese mice was treatment with the leptin antagonist peptide associated with a tendency for a reduction in tumor volume (ns Student’s t-test)." (PMID 25599228, 2015). "The anti-tumour action of LDFI was associated with the inhibition of several leptin-induced pathways such as JAK2, STAT3, AKT and MAPK and a reduction in Cyclin D1 expression." (PMID 25721149, 2015). "The associations between serum leptin and tumor biomarker expression were evaluated by Spearman’s correlation analysis." (PMID 24932291, 2014). "Leptin’s paracrine actions can further affect stromal cells and tumor associated macrophages, which express OB-R and secrete VEGF and IL-1, respectively." (PMID 24202338, 2013). "The expression of either protein was associated with greater tumor size (P=0.016 for leptin and P=0.002 for OBRs)." (PMID 23425972, 2013). "The authors linked the relative tumor resistance in EE mice to a significant decrease in the levels of leptin and increase in those of plasma adiponectin levels." (PMID 23272114, 2012). "Proangiogenic and mitogenic functions of leptin have been implicated in development and progression of different neoplasms." (PMID 21771332, 2011). "As metalloproteinases (MMPs) have been linked with the promotion of tumor invasiveness, we next examined leptin's effect in the production of MMPs-1, -9 and -13 by HepG2 cells." (PMID 20723213, 2010). "The expression of leptin or ObR was, at least numerically, associated with tumor size, being more frequent in large (> 10 mm) tumors (Table." (PMID 18945363, 2008). "In animal and human cell lines, leptin and leptin receptors have also been clearly associated with enhanced in vitro tumor proliferation and/or to in vitro and in vivo promotion of angiogenesis." (PMID 16504019, 2006). "These leptin-enriched EVs have been implicated in various stages of tumor progression." (PMID 40485730, 2025). "Due to these contradictory findings, future research may explore the underlying mechanism of PRAT-derived leptin involvement in tumor development and progression." (PMID 40227577, 2025). "For example, inhibiting the expression or activity of adipokines such as leptin or adiponectin, which have been implicated in promoting tumor growth and metastasis, could potentially hinder tumor progression." (PMID 41200178, 2025). "Additionally, higher leptin levels were associated with tumor ulceration and shorter DFI, while elevated ObR levels were linked to smaller tumors and ER-negative status." (PMID 41150099, 2025). "Leptin can also increase tumor-associated inflammation by upregulating pro-inflammatory cytokines." (PMID 41010935, 2025). "Leptin is involved in the loss of epithelial cell characteristics, promoting the expression of mesenchymal features and leading to the migration and invasion of tumor cells." (PMID 38255203, 2024). "The influence of leptin on tumor-associated macrophages (TAMs) is intriguing." (PMID 38255203, 2024). "Besides, leptin increase tumor‐associated macrophages (TAMs), such as increasing IL‐18 which activates the NF‐κB/NF‐κB1 signaling pathway that assist migration and invasion of BC cell." (PMID 38717954, 2024). "Besides adiponectin, obese individuals have a higher expression of leptin and its receptor which has been implicated in increasing the metastatic potential in the tumor microenvironment." (PMID 37800138, 2023). "Postoperative weight gain may be related to invasive tumor treatment, which damages the paraventricular nucleus and the suprachiasmatic nucleus, leads to loss of satiety, and inhibits the interaction of leptin, insulin, and intestinal hormones." (PMID 37324266, 2023). "Moreover, MMTV-Wnt-1 leptin-deficient mice (Lepob/ob) showed a reduction in tumor growth compared to wild-type mice." (PMID 37509120, 2023). "LEP is associated with tumor cell migration and invasion, as well as angiogenesis in some tumors." (PMID 36941557, 2023).
tumor (continued). "Moreover, there was a positive association between advanced tumor stages and leptin/leptin receptor plasma levels." (PMID 37942199, 2023). "Leptin deficiency caused reduced growth and tumor-initiating activity of transplanted tumors." (PMID 35563777, 2022). "Leptin also activates IL-8 production in tumor-associated macrophages, driving tumor progression." (PMID 35752704, 2022). "In addition to its traditional role in regulating appetite and energy expenditure, leptin signaling is implicated in promoting tumor cell proliferation and migration." (PMID 36381236, 2022). "Furthermore, the inflammatory profile of subcutaneous adipose tissue is associated with an increased release of leptin and resistin, supporting the progression of tumour cells and increasing the risk of lymph node metastasis." (PMID 35334544, 2022). "This indicates that leptin might mediate the link between CAAs and M2-like macrophages in high-fat diet-induced obesity-associated tumor metastasis." (PMID 33391518, 2021). "Additionally, leptin and leptin receptor-deficient animal models presented resistance to induced tumor development, corroborating the important role of leptin in tumorigenesis." (PMID 33371214, 2020). "Similarly, leptin deficiency was found to impair tumor-initiating cells and consequently tumor growth in obese mice." (PMID 33371274, 2020). "In particular, the adipose tissue-derived adipokine leptin has been strongly linked to tumor cell proliferation, migration, and metastasis, but the underlying mechanisms remain unclear." (PMID 33490070, 2020). "Leptin-induced Notch axis in PC was linked to leptin-induced tumor growth." (PMID 29719602, 2018). "Because both leptin and IL-1 are inflammatory and proangiogeneic factors that upregulate VEGF, the association between IL-1 and leptin could be a critical event for tumour angiogenesis." (PMID 27472371, 2016). "Increased leptin levels are associated with faster tumor growth in animal studies." (PMID 27525031, 2016). "Moreover, there are data that tumor expression of leptin is associated with chemotherapy resistance." (PMID 26467912, 2015). "It has been shown that tumor leptin mRNA expression may be associated with chemo-resistance; however it is also correlated to a therapy-independent better prognosis." (PMID 25857300, 2015). "Thus, to better understand the mechanisms underlying leptin-induced tumor growth, herein we investigated the potential role of autophagy in leptin-induced tumor growth and molecular mechanisms underlying autophagy induction." (PMID 25704884, 2015). "However, the detailed molecular mechanisms underlying leptin-induced tumor growth are not clearly understood." (PMID 25704884, 2015). "Adipose tissue also secretes leptin, which has been implicated in enhancing angiogenesis and, consequently, may also enhance tumour development." (PMID 26475132, 2015). "Therefore, the present study has further identified that autophagy activation would be a novel mechanism underlying leptin-induced tumor growth." (PMID 25704884, 2015). "Interestingly, in BC patients high intra-tumor ObR gene expression was strongly correlated with decreased relapse-free survival, indicating that susceptibility to leptin signaling is strongly associated with BC disease prognosis." (PMID 25360510, 2014). "Our study on the association of OBR and leptin expression with clinicopathological data demonstrated that PTC samples with positive staining for OBRs (P=0.002) or leptin (P=0.016) were associated with a larger tumor size." (PMID 23425972, 2013). "Conversely, a loss of leptin expression attenuates tumor growth." (PMID 22263109, 2012). "Moreover, in these patients, there was a clear correlation between disease stage and performance status with markers of inflammation, such as IL-6 whereas low leptin levels were more closely associated with tumor stage and IL-6 levels than BMI." (PMID 22518191, 2012).